CADM1 (cell adhesion molecule 1)
Diseases named in the same sentence as CADM1 in open-access papers (continued):
Sharing a sentence is not in itself a finding about the gene and the disease.
cancer (continued). "Despite the earlier identification of membrane-proximal cleavage of cell adhesion molecule 1 (CADM1) in cancers, the role of the membrane-bound fragment of CAMD1 (MF-CADM1) is yet to be clearly identified." (PMID 35805896, 2022). "CADM1 is mainly downregulated in malignant tumors of multiple organ systems due to promoter methylation." (PMID 34395444, 2021). "Many studies have shown that CADM1 interacts with a single non-coding RNA, such as microRNAs and lncRNAs, thereby participating in the regulation of the occurrence and development of malignant tumors." (PMID 34395444, 2021). "CADM1 is often involved in malignant tumors of multiple organ systems, such as the respiratory and digestive systems." (PMID 34395444, 2021). "The low expression of CADM1 in malignant tumors of multiple systems often involves the regulation of lncRNAs and miRNA." (PMID 34395444, 2021). "Several genes in the cell adhesion molecule category, such as CD44 and CADM1, were involved in cancer cell migration and the regulation of ECM adhesion." (PMID 32315343, 2020). "Promoter methylation of CADM1 has been shown to be one of the main mechanisms to drive the initiation and progression of various cancers." (PMID 29228687, 2017). "Regarding the three genes (WWOX, CADM1 and CCDC80) detected as SETDB2 target genes in our study, their loss or reduced expression has been reported in various cancers." (PMID 27572307, 2016). "In three HPV-positive cancer cell lines (SiHa, HeLa and CaSki), the average methylation level of CADM1 was 83.9%." (PMID 25845528, 2015). "We examined the DNA methylation status of the promoter region of CADM1 (nucleotides -444 to -305) to gain insight into the contribution of gene promoter methylation toward aberrant expression of CADM1 in HPV-positive cancer cell lines." (PMID 25845528, 2015). "Although much remains to be clarified regarding the aberrant methylation of CADM1, further studies should shed light on the mechanism of cancer development, as well as identify more effective cancer therapies." (PMID 25845528, 2015). "The CADM1 gene is frequently down regulated epigenetically in a variety of advanced-stage human cancers of the lung, prostate, liver, pancreas, and breast." (PMID 25845528, 2015). "SPARC, RECK, TNFAIP3 and CXCL14 were down-regulated (p < 0.05) in BCBM as compared to primary BC samples irrespectively of the cancer subtype, while for CADM1, this correlation was found in HR positive and TNBC samples." (PMID 24833255, 2014). "CADM1 expression is significantly reduced in several cancers and inversely correlated with the disease progression." (PMID 22438059, 2012). "Here, we designed and analyzed a multiplex qMSP assay for three genes whose methylation was previously found to be informative for cervical (pre)cancer (i.e. CADM1, MAL and hsa-miR-124-2) as well as a reference gene β-actin." (PMID 23176198, 2012). "CADM1 (cell adhesion molecule 1) is a tumor suppressor gene identified in non-small cell lung cancer (NSCLC), but also implicated in other human cancer diseases." (PMID 22701659, 2012). "This is consistent with the frequent silencing of CADM1 observed in human cancer types, both of epithelial and hematopoietic origin." (PMID 22553910, 2012). "CADM1 is expressed universally in human tissues and is frequently silenced in a variety of human carcinomas." (PMID 21980425, 2011). "Our data show that repression of CADM1 is an early event in HPV-driven disease, preceding hypermethylation of the CADM1 transcriptional promoter that is frequently observed in HPV-driven cancers, demonstrating a novel mechanism of HPV-induced host cell transcriptional reprogramming." (PMID 39869645, 2025).
cancer (continued). "Evidence from other cancer types has further implicated CADM1 in the repression of tumorgenicity through the negative regulation of G1/S transition, which is consistent with the proportion of triple positive CSCs observed in G0/G1 arrest herein." (PMID 36316307, 2022). "CADM1 seems to play different roles depending on the cancer type." (PMID 35805896, 2022). "The results of mechanistic experiments suggested that exosome-mediated miR-148a may promote cancer cell proliferation and metastasis by targeting cell adhesion molecule 1 (CADM1) to activate the STAT3 pathway." (PMID 35999601, 2022). "Taken together, CADM1 could be a potential biomarker for early diagnosis and a target for cancer treatment in future clinical practices." (PMID 34395444, 2021). "Recently, studies have shown that malignant tumors involving multiple systems lack CADM1 expression, which could be related to epigenetic changes in CADM1." (PMID 34395444, 2021). "Therefore, for the diagnosis and targeted therapy of multiple malignant tumors, CADM1 would be a promising biomarker." (PMID 34395444, 2021). "CADM1 actively participates in the invasion and migration of a variety of cancers." (PMID 34395444, 2021). "Summary of the clinical characteristics of CADM1 in malignant tumors." (PMID 34395444, 2021). "CADM1 could be an important biomarker, and it may have an important role in early diagnosis and targeted therapy of malignant tumors." (PMID 34395444, 2021). "CADM1, a member of one of the cell adhesion molecule families (CAMs), nectin-like molecules (Necl), is involved in the establishment of cell adhesion and is also known to play a role as a tumor suppressor in various human cancers." (PMID 33114686, 2020). "On the other hand, CADM1 is shown to be a good prognostic marker in other cancers." (PMID 32195182, 2020). "CADM1 associates with 4.1B/DAL-1 through the 4.1B binding motif, while loss of the CADM1–4.1B/DAL-1 complex may affect cancer cell adhesion and enhance cancer cell invasion and/or metastasis." (PMID 31492173, 2019). "Of note, all 5 cancers were CADM1/MAL/miR124-2 methylation positive." (PMID 29069800, 2017). "Downregulation of CADM1 gene leads to metastasis and cancer progression." (PMID 27933097, 2016). "Previous studies have found that CADM1/TSLC1 expression was absent or reduced in a variety of malignant tumors and was associated with growth and invasion in malignancy." (PMID 26880895, 2016). "CADM1 is downregulated in many cancers, frequently via promoter hypermethylation." (PMID 25845528, 2015). "Thus, CADM1 appears to act as a suppressor of cancer cell invasion and metastasis by its activity in the formation and maintenance of adhesion-based epithelial cell structure." (PMID 24503895, 2014). "CADM1 is expressed diffusely in the lateral membrane of cell-cell attachment sites in polarized epithelia, whereas, expression of CADM1 is frequently lost or reduced in a variety of advanced-stage human cancers of the lung, prostate, liver, pancreas, and breast." (PMID 24503895, 2014). "CADM1 is non-redundant in human physiology and has been implicated in several diseases including cancer, autism spectrum disorder and venous thrombosis." (PMID 22438059, 2012). "Stenotrophomonas, an opportunistic pathogen with increased colonization/infection in cancer patients, exhibited extensive positive associations with the hypermethylation of genes, including multiple TSGs in CRC, such as ESR1, RASSF5, DIRAS1, CADM1, ST5, GJB2, FAM172A, and HIVEP3." (PMID 38840170, 2024). "Furthermore, CADM1 overexpression inhibits cancer cell metastasis and inhibits cancer progression." (PMID 34395444, 2021). "In this connection, it is noteworthy that we have previously reported that overexpression of CADM1 in MDCK cells suppresses hepatocyte growth factor (HGF)-induced epithelial-mesenchymal transition (EMT), which is a well-known phenomenon associated with cancer cell invasion and metastasis." (PMID 24503895, 2014).
cancer (continued). "CADM1 methylation exhibited a stepwise increase across the NILM, LSIL, HSIL, and carcinoma groups, with a statistically significant elevation in cancer cases (p < 0.001)." (PMID 40564169, 2025). "CADM1 methylation remained low or undetectable in the NILM, LSIL, and HSIL groups, with a significant increase observed in carcinoma cases." (PMID 40564169, 2025). "CADM1 was differently expressed in K1, BCPAP, TPC1 and IHH4 cancer cell lines, among which CADM1 was lowly expressed in IHH4 and TPC1." (PMID 36523593, 2022). "For example, modifications of nuclear DNA and its regulatory proteins (IGF2, SLC22A18, PHLDA2, CDKN1C, and KCNQ1) and proteins involved in cancer development (MYCN, IGSF4, and CADM1) are known to be located on human chromosome 11." (PMID 35538492, 2022). "Instead, the analysis showed that cancer stage was affected by HIV status (χ2 = 19.93; P = 0.001), RARB (χ2 = 7.32; P = 0.002), and CADM1 (χ2 = 12.68; P = 0.013) methylation status." (PMID 33718129, 2021). "Seven of these predicted proteins (NCAM1, CNTN1, SCG2, CADM1, IL-8, NPTX1, and APOD) were identified in five databases (SignalP 4.1, SecretomeP 2.0, Vesiclepedia, Human Cancer Secretome, and Plasma Proteome), giving support to their relevance in NSCLC." (PMID 31455042, 2019). "Compared to normal cytology with histology ≤ LSIL, the methylation levels of CADM1 and MAL increased 5.3 and 6.2 folds in CINII/III, and 143.5 and 454.9 folds in carcinomas, respectively." (PMID 30608989, 2019). "Integrin α4β1 and its adhesion receptor, cell adhesion molecule-1 (VCAM-1), were also reported to play a role in the interaction between cancer cells and the mesothelial cells." (PMID 26223322, 2015). "Notably, it has also been shown that downregulation of CADM1 in HPV-driven cancer is due to hypermethylation of a CpG island at the CADM1 TSS and that sequential hypermethylation at the CADM1 TSS correlates with HPV-driven cancer stage." (PMID 39869645, 2025). "In contrast, CADM1 and MAL showed no significant diagnostic value for carcinoma detection in this context." (PMID 40564169, 2025). "In clinician-collected cervical samples, DNA methylation of MAL and miR124-2 was significantly higher in HSIL/cancer compared with normal/LSIL samples while the methylation of CADM1 failed to distinguish between cytology grades." (PMID 38904134, 2024). "Functional experiments, as well as single-cell RNA sequencing (scRNA-seq), further indicated that TMZ treatment resulted in cellular heterogeneity which induced quiescent cancer stem cells (CSCs), labeled by NES+/SOX2+/CADM1+ and acting as a major contributor of TMZ resistance." (PMID 36316307, 2022). "This targeted the cell adhesion molecule 1 (CADM1) when compared to EVs isolated from healthy volunteers, suggesting that miR-148a might be involved in cancer invasion." (PMID 32384712, 2020). "Meanwhile, CADM1 and NFAT5 are critically involved in the migration and invasion of cancer cells." (PMID 33374139, 2020). "Cell adhesion molecule 1 (CADM1/TSLC1), belonging to the immunoglobulin superfamily, is involved in normal cell adhesion, proliferation, and differentiation and plays an important role in the suppression of malignant tumor cell invasion and metastasis." (PMID 26880895, 2016). "This loss of CTCF binding is coincident with a switch in epigenetic mark enrichment, from an active to inactive chromatin state, and with reduced CADM1 expression, but not with increased CpG hypermethylation as has been described in HPV-driven cancers." (PMID 39869645, 2025). "Within our cohort of 24 age-matched HTLV-1-infected individuals without malignancy (in whom the PVL ranged from undetectable to 79 copies per 100 PBMC), the OCI-flow of CADM1+CD3+ cells did not exceed 0.7." (PMID 27893842, 2016). "It is known that WWOX and CADM1 but not CCDC80 have dense CpG islands in their promoter regions and hypermethylation at the promoter regions of WWOX and CADM1 has been reported in cancer cells." (PMID 27572307, 2016).
cancer (continued). "Only a small increase in CpG methylation of the CADM1 promoter between HPV negative controls and cells harvested between 14–80 passages after E6/E7-mediated immortalisation was observed; indeed increased methylation was only observed in the control HPV+ cancer cell line (SiHa)." (PMID 39869645, 2025).
infection (16 papers, 2005 to 2025). The state of being infected such as from the introduction of a foreign agent such as serum, vaccine, antigenic substance or organism. "HPV-mediated repression of CADM1 is therefore likely to be important in persistence of infection by altering both epithelial tissue integrity and immune cell attraction and activation within the lesion." (PMID 39869645, 2025). "Multiple vascular adhesion proteins were induced rapidly during infection, such as CADM1, ICAM1, and VCAM1." (PMID 35913192, 2022). "Our recent findings suggest that cell surface expressed Cell adhesion molecule 1 (CADM1) is critical for KSHV de novo infection-induced NF-κB activation." (PMID 33182552, 2020). "Thus, the combination of markers of clonal expansion (TCRVβ+ and CD7low) and infection (CADM1+) allows sensitive detection and accurate quantification of expanded ATL clones." (PMID 27893842, 2016). "Recent studies have shown that the combination of methylation-mediated silencing of CADM1 (cell adhesion molecule 1) and MAL (T-lymphocyte maturation-associated protein) promoter genes in cervical scrapes seems to be related to the duration of hrHPV infection and the severity of the SIL/CIN lesion." (PMID 31067838, 2019). "Thus, methylation analyses of CADM1, MAL, and miR124 seem to be able to distinguish hrHPV-positive patients with transforming lesions at short-term risk of progression from women with clinically irrelevant infections." (PMID 31067838, 2019). "Because LUHMES express CADM1/2 and NECTIN1/PVRL1 (Table A1), it is plausible that the measles virus similarly exploits these cell-surface proteins to achieve infection in LUHMES." (PMID 40733616, 2025). "Although CADM1 and IKKβ and IKKε kinases are critical for NF-κB activation upon KSHV de novo infection, the mechanisms of CADM1 and IKKβ and IKKε activation are unclear." (PMID 33182552, 2020). "Our recent findings suggest that Cell Adhesion Molecule 1 (CADM1), which is highly induced during KSHV de novo infection, is essential for vFLIP to maintain chronic NF-κB activation in PEL cells." (PMID 33182552, 2020). "The identity of these CADM1+CD11b− cells require further investigation, and one animal (AZ48) had a high proportion of SLAII+CD172a+CADM1+CD11b− cells that were infected, which suggests a contribution of infection-induced cell death." (PMID 41510007, 2025). "While the CD22-CD45 signaling in the healthy group, involved in the B cell maturation process was absent in the infected and recovered group, the CD99 and CADM1 signaling observed in the infected group were absent post- infection." (PMID 36532041, 2022). "However, upon the infection of HTLV-1, CADM1 is transcriptionally activated via the binding of the NF-κB transcription factors to the CADM1 promoter (this study)." (PMID 30837480, 2019). "In addition, if CADM1 is required for IKKβ and IKKε early activation during KSHV de novo infection is unknown." (PMID 33182552, 2020). "To examine CADM1 expression in KSHV-infected cells, we first infected HeLa cells, human umbilical vein endothelial cells (HUVEC), and primary human B-cells isolated from peripheral blood mononuclear cells (PBMCs) from healthy volunteers with KSHV at 0.1 multiplicity of infection (MOI)." (PMID 29698475, 2018).
adenocarcinoma (5 papers, 2005 to 2025). A common cancer characterized by the presence of malignant glandular cells. "Of these, survival was best predicted by CDK1 (p<1E-16), CD24 (p<1E-16) and CADM1 (p = 7E-12) in adenocarcinomas and by CCNE1 (p = 2.3E-09) and VEGF (p = 3.3E-10) in all NSCLC patients." (PMID 24367507, 2013). "The potential predicted targets of miR-192-5p include CADM1, SBSPON and FAM229B, which were down-regulated in adenocarcinoma from our transcriptome sequencing data." (PMID 33024199, 2020).
CNS tumor (1 paper, 2021). "For brain and CNS tumor samples, CADM1, CADM2, NECTIN1, and NECTIN3 were downregulated, whereas NECTIN2 was overexpressed." (PMID 34925438, 2021).
CADM1 also shares sentences with these, for which no sentence is quoted: prostate carcinoma (5 papers); attention deficit-hyperactivity disorder (3); Cognitive impairment (3); colon cancer (3); schizophrenia (3); skin cancer (3); asthma (2); malaria (2); male infertility (2); neurodevelopmental disorder (2); psychiatric disorder (2); Achalasia (1); adenoid cystic carcinoma (1); Adenomatous Polyposis Coli (1); Allergy (1); anal carcinoma (1); anal disease (1); asthenozoospermia (1); atrial fibrillation (1); autoimmune disease (1); Autoimmunity (1); basal cell carcinoma (1); Burkitt lymphoma (1); cervical tumors (1); cervix squamous cell carcinomas (1); chondrosarcoma (1); chronic lymphocytic leukemia (1); clear cell renal cell carcinoma (1); cognitive disorder (1); colon adenocarcinoma (1).
A further 55 diseases each share a sentence with CADM1 in 1 paper.